CCN3 (cellular communication network factor 3)
Diseases named in the same sentence as CCN3 in open-access papers (continued):
Sharing a sentence is not in itself a finding about the gene and the disease.
Obesity (13 papers, 2013 to 2023). Accumulation of substantial excess body fat. "The study demonstrated that CCN3 was upregulated in adipose tissue of obese humans and mice, and there was a positive association between obesity-related inflammation and CCN3 plasma levels." (PMID 37919772, 2023). "Excess CCN3 is associated with the induction of obesity, insulin resistance, and impaired adipocyte differentiation." (PMID 34948212, 2021). "Given the known roles and effects of CCN3 in haematopoiesis and as an adipokine modulator of immune function, it remains relevant to understand its expression profile particularly considering the pathogenic role of both obesity and the adaptive immune system in multiple sclerosis." (PMID 33222687, 2020). "Previous studies have shown a link between NOV/CCN3 (an adipokine) and obesity, insulin resistance, and inflammation." (PMID 37919772, 2023). "Subjects with obesity showed significantly higher values of NOV/CCN3, leptin and FGF21, and significantly lower values of adiponectin than normal-weight subjects." (PMID 38137540, 2023). "In our previous report, we showed that the CCN3 expression level was correlated with age, and that elderly people who are prone to obesity are more likely to develop osteoarthritis." (PMID 36499638, 2022). "The crosstalk of the adipose tissue-specific deletion of NOV/CCN3 improved cardiovascular function, representing a novel therapeutic strategy for obesity-related cardiometabolic dysfunction." (PMID 36231029, 2022). "Another member of the family, CCN3/NOV, has also been reported to be an adipocytokine involved in obesity-associated insulin resistance." (PMID 34948212, 2021). "Plasma levels of CCN3 reflect many cellular sources including adipose tissue and are known to correlate to increasing BMI and obesity." (PMID 33222687, 2020). "CCN3 is expressed by adipocytes and is believed to contribute to obesity-related inflammation and conditions including type 2 diabetes, sleep apnoea and obesity-induced cardiomyopathy." (PMID 33222687, 2020). "This review focuses on the effects of omentin, vaspin, cardiotrophin-1, Tumor necrosis factor-like Weak Inducer of Apoptosis (TWEAK) and nephroblastoma overexpressed (NOV/CCN3) on obesity and diabetes." (PMID 28809783, 2017). "These authors also reported that NOV/CCN3 contributed to the development of obesity-induced insulin resistance, based on their studies in knock-out mice." (PMID 28809783, 2017). "Notably, our findings lend support to the notion that CCN3 levels in CAD patients increase independently of obesity and insulin resistance parameters, thus potentially serving as a robust biomarker for the prognosis of CAD patients." (PMID 37919772, 2023). "In this context, CCN3, which is a CCN family member with molecular functionalities counteracting CCN2, needs to be investigated, as the hormonal function of CCN3 and its association with obesity, diabetes, and insulin resistance were pointed out." (PMID 35955724, 2022). "Moreover, excess CCN3 induces obesity, insulin resistance, and disrupt pancreatic islets; this is similar to CCN5 knockout, demonstrating the contrasting roles played by CCN3 and CCN5 again." (PMID 34948212, 2021). "Thus, our findings suggest that CCN3 may serve as a potential therapeutic target for improving insulin sensitivity and preventing obesity in CAD patients." (PMID 37919772, 2023). "Moreover, Ccn3 expression is increased in lymphocytes from patients with obesity." (PMID 23705021, 2013). "Subjects with obesity showed an altered serum cytokine profile, characterized by increased levels of leptin, FGF21 and NOV/CCN3, a decreased level of adiponectin, and similar levels of vaspin and chemerin compared to normal-weight subjects." (PMID 38137540, 2023).
Obesity (continued). "Moreover, previous studies have linked CCN3 to various disorders such as insulin resistance, obesity, non-alcoholic fatty liver disease, and inflammation, however, the relationship between CCN3 serum levels and CAD has not been explored thus far." (PMID 37919772, 2023).
breast carcinoma (12 papers, 2012 to 2023). "Contrarily, has-miR-30c expression increases the invasiveness of metastatic neoplastic cells and is associated with poor prognosis in breast cancer by inhibiting NOV/CCN3 regulatory proteins." (PMID 34187521, 2021). "Several reports have investigated the association of CCN3 expression with clinical parameters of patients with breast cancer." (PMID 22427255, 2012). "High CCN1/CCN3 or CCN2/CCN3 mRNA ratios were found to be associated with a highly metastatic phenotype in breast cancer cells." (PMID 22427255, 2012). "In addition, in an analysis using a public database, overexpression of CCN3 was associated with poor clinical outcomes in patients with basal-like breast cancer." (PMID 36737605, 2023). "Overexpression of CCN3 is associated with breast cancer metastasis to distant organs." (PMID 34940056, 2021). "The rate of CCN3 alterations including copy number amplification and high mRNA expression accounted for 21 and 25% of entire breast cancer patients in TCGA and METABRIC, respectively." (PMID 36737605, 2023). "We verified overexpression of CCN3 in the conditioned medium (CM) from TNBC cell lines with a panel of breast cancer cell lines." (PMID 36737605, 2023). "We found that CCN3 is overexpressed in TNBC and associated with poor prognosis of breast cancer patients." (PMID 36737605, 2023). "Consistent with previous reports, our results also showed that CCN3 regulates breast cancer metastasis through the regulation of EMT and cell migration." (PMID 36737605, 2023). "For example, in breast cancer cells, CCN3 increased cell proliferation by upregulating the expression of cyclin D1." (PMID 37373471, 2023). "To identify the clinical implications of CCN3 in breast cancer, we checked the genetic alterations of CCN3 in breast cancer patients using a public database." (PMID 36737605, 2023). "In contrast, in another study with a cohort with 122 breast cancer cases, both CCN2 and CCN3 levels were rather repressed in aggressive breast cancer tissues compared to those in the normal ones." (PMID 35682564, 2022). "Recent evidence suggests that bone metastatic breast cancer cells can reprogram osteoblasts in the bone marrow niche to produce altered amounts of decorin and CCN3, which leads to the inhibition of tumor cell proliferation via upregulation of p21 expression." (PMID 34831167, 2021). "NOV/CCN3 expression, which protects cells from invasion, is known in patient tumors to inversely correlate with advanced breast cancer and metastasis." (PMID 25120384, 2014). "NOV/CCN3 expression in patients is known to inversely correlate with advanced breast cancer and metastasis." (PMID 25120384, 2014). "Given the ability of CCN3 to modulate the differentiation status and activity of bone resident cells, it is interesting to note that breast cancer cells that metastasize to bone and induce bone destruction select for high levels of CCN3 expression." (PMID 22427255, 2012). "In breast cancer-derived cell lines, low expression of CCN3 was also reported in the aggressive MDA-MB-231 human cell line when compared to the less invasive MCF-7 line." (PMID 22427255, 2012). "Using MCF-7 cell line as a breast cancer model, CCN3 was reported to be a direct target of estrogen." (PMID 22427255, 2012). "Interestingly, CCN3 expression was significantly correlated with vimentin in breast cancer cell lines, which is a mesenchymal marker that has been associated with epithelial to mesenchymal transition (EMT) and metastasis." (PMID 36737605, 2023). "We confirmed that TNBC-specific upregulation of CCN3 among other breast cancer subtypes." (PMID 36737605, 2023). "In addition, it has been reported that CCN3 induces actin cytoskeleton organization in breast cancer." (PMID 36737605, 2023). "This domain of CCN3, 4, 5 was also reported involving tumorigenesis, especially in breast cancer." (PMID 31321242, 2019).
breast carcinoma (continued). "Interestingly, in another study, a microarray profile derived from 58 breast cancer metastases showed CCN3 to be highly expressed in bone metastases when compared to other metastases (lung, brain, and liver)." (PMID 24551846, 2014). "In our own work, we also have shown that CCN3 is expressed in bone metastasis samples from patients with breast cancer and have identified CCN3 as a gene highly expressed at the mRNA and protein levels in 4T1 murine breast cancer cells selected for their ability to metastasize to bone." (PMID 22427255, 2012). "The first hint that CCN3 may play a role in organ-specific metastasis came from the analysis of gene expression profiles derived from 58 breast cancer metastases." (PMID 22427255, 2012). "Moreover, CCN3 was highly expressed in breast cancers from patients who had relapsed following tamoxifen treatment versus tumors from those that did not." (PMID 22427255, 2012). "While the expression of CCN proteins varies in different cancer types, CCN1, CCN2, CCN3 and CCN4 participate in tumor development and act as oncogenes, but CCN1, CCN3, CCN5, and CCN6 inhibit tumor growth and play tumor-suppressive roles in breast carcinomas." (PMID 34940056, 2021). "Interestingly, the ability of CCN3 to promote the formation of osteolytic bone metastases may reflect the fact that breast cancer cells colonizing the bone would contribute to significantly elevated levels of CCN3, which would tip the balance towards osteoclastogenesis." (PMID 22427255, 2012). "CCN1, CCN3, CCN5, CCN6 play a critical role in survival in breast cancer." (PMID 34940056, 2021). "CCN1, CCN2, CCN3, and CCN4 are pro-tumorigenic and may be responsible for human breast carcinoma; while CCN1, CCN3, CCN5 and CCN6 have anti-tumorigenic effects." (PMID 34940056, 2021). "Breast cancer cells, once nested to bone, undergo partial osteomimicry by acquisition of typical bone cell markers including ICAM-1, CDH11, OPN, osteonectin (SPARC), osteocalcin (BGLAP) and cellular communication network factor 3 (CCN3)." (PMID 34831167, 2021). "The pro-tumorigenic CCN1, CCN2, CCN3, and CCN4 may lead to human breast cancer, although the anti-tumorigenic actions of CCN5 and CCN6 are also present." (PMID 34940056, 2021). "CCN1, CCN3, CCN5 and CCN6 may play dual roles; their expression can inhibit breast cancer growth, and their absence can induce carcinoma." (PMID 34940056, 2021). "This is in contrast to our findings in which we observed high CCN3 levels in the context of low CCN1 and CCN2 expression in bone metastatic breast cancer cells and also contrasts with the observation that human breast cancer bone metastases that display high CCN3 mRNA expression." (PMID 22427255, 2012).
Ewing sarcoma (9 papers, 2006 to 2023). A small round cell tumor that lacks morphologic, immunohistochemical, and electron microscopic evidence of neuroectodermal differentiation. "Expression of CCN3 was associated with a significant higher risk of developing lung and bone metastasis in Ewing’s sarcoma." (PMID 28575190, 2018). "CCN3 is expressed in approximately 30% of all Ewing sarcoma cases, and its expression is associated with a lower survival rate." (PMID 24551846, 2014). "While CCN3 is expressed in approximately 30% of Ewing’s sarcomas, it is associated with shorter disease free survival." (PMID 22427255, 2012). "Similarly, high CCN3 expression is also associated with a poor outcome in Ewing’s Sarcoma and elicits enhanced migratory and invasive responses in these cells." (PMID 22427255, 2012). "In addition, CCN3 has been implicated as a poor prognostic marker in several primary bone cancers, including osteosarcoma and Ewing’s sarcoma." (PMID 22427255, 2012). "Microarray analyses on 30 Ewing’s tumors, coupled with immunohistochemistry on 125 cases that possessed sufficient clinical data and follow-up, revealed that low levels of CCN3 expression were associated with better patient prognosis when disease free and overall survival was considered." (PMID 22427255, 2012). "We had previously reported that detection of CCN3 in primary Ewing tumors was associated with a higher risk of developing metastasis It will be interesting to check whether truncated CCN3 proteins were produced in these samples." (PMID 16895594, 2006). "NOV (CCN3) is a secreted, abundantly expressed extracellular matrix-associated signaling protein capable of regulating cellular activities including proliferation, migration, and cell adhesion and reduces the proliferation of glioblastoma cells and Ewing’s sarcoma." (PMID 30813947, 2019). "Ewing’s sarcoma cell line (TC71) engineered to overexpress CCN3 displayed decreased cell proliferation in vitro, growth in soft agar and tumorigenicity when injected into mice." (PMID 22427255, 2012). "Immunohistochemistry on 170 human Ewing’s sarcoma samples revealed that CCN3 was more highly expressed in recurrences (6/8) and metastases (8/10) when compared to the primary tumor (79/152)." (PMID 22427255, 2012). "The case of Ewing tumors was of particular interest because in this sytem CCN3 was acting as a double edge sword." (PMID 16504021, 2006). "In Ewing’s sarcoma, forced expression of CCN3 resulted in the suppression of cell proliferation." (PMID 36737605, 2023). "Finally, an immunohistochemistry study on 170 human Ewing sarcoma specimens showed that the expression of CCN3 was higher in recurrences and metastases than in primary tumors." (PMID 24551846, 2014). "Given these functions, it is not surprising that CCN3 has been implicated in the progression of primary bone cancers such as osteosarcoma, Ewing’s sarcoma and chondrosarcoma." (PMID 22427255, 2012).
melanoma (9 papers, 2006 to 2025). A malignant, usually aggressive tumor composed of atypical, neoplastic melanocytes. "CCN3 was overexpressed in metastatic melanoma compared with the primary tumor and was associated with higher metastatic potential of melanoma cells." (PMID 31029128, 2019). "By contrast, another study suggests that progression of melanoma is associated with CCN3 downregulation; these differences highlight the complexity of CCN biology in tumours." (PMID 18789696, 2008). "Ccn3 has been implicated in multiple immune-related diseases, including systemic sclerosis, and is known to promote invasion and metastasis in various solid cancers, such as breast, prostate, bladder, and melanoma." (PMID 41008788, 2025). "The decreased expression of CCN3 was investigated in the invasion melanoma cells, and CCN3 transduction lessened the invasion through restraining the MMP-2 and MMP-9 activities." (PMID 34393649, 2021). "Likewise, CCN3 is highly expressed in both visceral and nodal melanoma metastases and it has been proposed that it regulates dissemination of the tumour cells through the interaction of tumour cells with the ECM." (PMID 18789696, 2008). "Interestingly, the expression of truncated nuclear CCN3 proteins is correlated to the metastatic potential of melanoma tumor cells (Rodolfo M. personal communication)." (PMID 16895594, 2006). "Vallacchi and colleagues showed that the expression of CCN3 did not affect the tumor growth of melanoma." (PMID 36737605, 2023).
Insulin resistance (8 papers, 2013 to 2025). Increased resistance towards insulin, that is, diminished effectiveness of insulin in reducing blood glucose levels. "CCN3 is associated with thinness due to insulin resistance and is known to negatively regulate bone regeneration and maintain bone density." (PMID 40395806, 2025). "Further studies with genetically-engineered mice with either loss- or gain-of-function mutations would be required to further explore the role of CCN3 in insulin resistance and β-cell function." (PMID 23705021, 2013). "To investigate whether the increase in CCN3 levels are causally linked to impaired β-cell function in the etiology of diabetes/insulin resistance, we evaluated the effects of CCN3 on β INS832/13-cell proliferation." (PMID 23705021, 2013). "In summary, our results identify Ccn3 as a novel transcriptional target of FoxO1 that could underlie the adaptive response to insulin resistance." (PMID 23705021, 2013). "We also observed increased CCN3 immunoreactivity in db/db and Irs2−/− mice, two genetic models of insulin resistance with β-cell failure." (PMID 23705021, 2013). "Accordingly, we show that expression of Ccn3 is increased in genetic mouse models of insulin resistance." (PMID 23705021, 2013). "The fact that CCN3 is up-regulated in insulin resistance and secreted by pancreatic β-cells is consistent with a model in which circulating CCN3 would act locally as well as distally to mediate the adaptation to this metabolic stress." (PMID 23705021, 2013). "In pancreatic islets, CCN3 expression is upregulated in animal models of insulin resistance." (PMID 34948212, 2021). "The role of CCN3 in β-cell mass and function as well as in insulin resistance could be of great clinical importance." (PMID 23705021, 2013).
osteosarcoma (8 papers, 2012 to 2021). A usually aggressive malignant bone-forming mesenchymal neoplasm, predominantly affecting adolescents and young adults. "The cadherin family of genes is associated with CCN3, which has been found to have prognostic value in Osteosarcoma." (PMID 30991985, 2019). "In addition, another study showed that CCN3 was expressed in primary tumors of osteosarcoma patients and that a high CCN3 expression level was associated with an increased risk of developing lung metastases." (PMID 24551846, 2014). "IHC revealed that eight normal specimens have high CCN3 expression, and 34 osteosarcoma specimens have high CCN3 expression (p<0.0001)." (PMID 32667904, 2020). "This clinical correlation is in agreement with the recent observation that CCN3 can enhance the migratory properties of osteosarcoma cells, which involves αvβ5 integrin-mediated upregulation of COX-2 expression." (PMID 22427255, 2012). "Using osteosarcoma derived cell lines; CCN3 expression was found to be inversely correlated with ALP expression." (PMID 22427255, 2012). "In osteosarcoma, CCN3 enhances the malignant phenotype of these cancer cells by limiting the extent of osteoblastic differentiation and promoting their migratory and invasive properties." (PMID 22427255, 2012). "CCN3 deserves separate mention as its role in osteosarcoma is controversial." (PMID 34228239, 2021). "As observed in osteosarcoma, the role of CCN3 in Ewing sarcoma is controversial." (PMID 34228239, 2021). "For instance, in osteosarcoma, high expression of CCN3 is significantly correlated with poor prognosis, and CCN3 may increase cell motility and MMP-13 expression through the integrin-dependent pathway." (PMID 29061995, 2017). "CCN4 also showed similar correlation like CCN1 and CCN3 in osteosarcoma." (PMID 24551846, 2014). "Interestingly, primary tumors of osteosarcoma patients, who developed lung metastases, presented with high CCN3 expression." (PMID 22427255, 2012). "In agreement with this hypothesis, CCN3 mRNA levels are increased in osteosarcoma cell lines and tumor tissues when compared to osteoblasts." (PMID 22427255, 2012). "Moreover, CCN3 has been shown to be upregulated in osteoblast-like osteosarcoma Saos-2 and OS7 cell lines." (PMID 22427255, 2012). "Thus, it has been hypothesized that high CCN3 expression in osteosarcoma might activate Notch signaling, resulting in osteosarcoma cells being locked into an early stage of osteoblastic differentiation." (PMID 22427255, 2012). "CCN1, CCN2, CCN3 and CCN4 are all poorly expressed in healthy adult bony tissues, but they are up regulated in primary samples as well as osteosarcoma cell lines." (PMID 34228239, 2021).